IL1B (interleukin 1 beta)
Diseases named in the same sentence as IL1B in open-access papers (continued):
Sharing a sentence is not in itself a finding about the gene and the disease.
colon carcinoma (continued). "The interaction between colon cancer cells and inflammatory cells promotes secretion of the release of IL-1β from immune cells." (PMID 27057094, 2016). "IL-1β has recently been reported to stimulate the expression of CFTR in T84 colon carcinoma cells, through NF-κB signalling." (PMID 26594334, 2015). "IL-1β also reported to promote epithelial-mesenchymal transition, stemness and invasiveness of colon cancer cells through Zeb factors." (PMID 26556872, 2015). "Another cytokine involved in cancer stem cell regulation is IL-1β, which can increase the sphere-forming capability of colon cancer cells in a serum-free medium." (PMID 25590298, 2015). "Another study indicated that IL-1β stimulates COX-2 production in cancer associated fibroblasts, leading to an increase in the proliferation and invasive capabilities of colon cancer cells." (PMID 24474192, 2014). "The PCT stimulators TNFα and IL-1β are actively involved in the pathogenesis of colon cancer and have been proposed as therapeutic targets for anti-cancer therapy." (PMID 23937962, 2013). "This inactivation of IL-1β suppresses inflammation and, in turn, Wnt signaling activation in colon cancer epithelial cells required for the progression of colon tumors." (PMID 24084056, 2013). "IL-1β is upregulated in colon cancer, and patients with IL-1β-producing tumors generally possess a bad prognosis (55, –57)." (PMID 23847622, 2013). "The results of the present study revealed a distinct pattern of basal and IL-1β-stimulated expression of MMPs and TIMPs mRNA in human colon carcinoma cells." (PMID 22415590, 2012). "Here we show that active Wnt signaling in colon cancer cells, and Wnt-dependent stabilization of Snail specifically, are required for tumor cells to stimulate macrophages to produce IL1β." (PMID 23029025, 2012). "Recent studies have shown that the interaction between colon cancer cells and immune cells induces secretion of IL-1β from immune cells." (PMID 23174018, 2012). "In the present study, the effect of IP6 on the expression of MMP and TIMP genes was evaluated in unstimulated and IL-1β-stimulated colon cancer cell line Caco-2." (PMID 22415590, 2012). "We reported that colon cancer cells, via a soluble factor, activate macrophages to secrete IL1β, which in turn promotes β-catenin/TCF4 transcriptional activity in the cancer cells and stimulates their growth." (PMID 23029025, 2012). "IL-1β levels are increased in a variety of cancers including colon cancer, one of the most common fatal cancers." (PMID 23174018, 2012). "Here, we provide direct evidence that IL-1β promotes self-renewal of colon cancer cells as well as their acquisition of EMT phenotype, and this induction of CSC and EMT phenotypes was mediated by Zeb1." (PMID 23174018, 2012). "We found that IL-1β can increase sphere-forming capability of colon cancer cells in serum-free medium." (PMID 23174018, 2012). "Together, these data confirmed that colon cancer cells activate macrophages via a Wnt/Snail-regulated factor, which is required for the production of IL1β." (PMID 23029025, 2012). "To identify the factors that mediated IL-1β-induced EMT in colon cancer cells, we examined the expression patterns of E-cadherin transcriptional repressors using rt-PCR." (PMID 23174018, 2012). "As sphere formation and growth represent the ability of cell self-renewal, these data suggest that IL-1β promotes self-renewal capacity in colon cancer cells, a critical characteristic of CSCs." (PMID 23174018, 2012). "We showed that macrophage-derived IL1β promotes Wnt signaling in colon cancer cells and thus regulates their growth and survival." (PMID 23029025, 2012). "Soluble form of IL-6R was secreted from the colon cancer cell line itself, and sIL-6R secretion was upregulated by IL-1β stimulation." (PMID 20823887, 2010). "We showed that pharmacological inhibition of GSK3β or IL-1β mediated inhibition of GSK3β, were sufficient to elevate the levels of Snail in colon cancer cells." (PMID 20661477, 2010).
colon carcinoma (continued). "The analysis of 70 metastatic colon tumors revealed that colon tumors that harbor mutant kRas have higher levels of IL-1β than tumors with WT kRas." (PMID 20661477, 2010). "The levels of IL-1β are increased in colon cancer patients harboring mutant kRas and elevated levels of IL-1β correlate with the resistance to cetuximab." (PMID 20661477, 2010). "A direct correlation between ST3Gal III levels, SLex levels and colon cancer cell adhesion to IL-1β activated human umbilical vein endothelial cells (HUVEC) has been described." (PMID 20824144, 2010). "We recently established that macrophages promote Wnt signaling in colon cancer cells and thus enhance their proliferation, and demonstrated that macrophages exert their protumorigenic activity mainly through the release of IL-1β." (PMID 20661477, 2010). "We showed that macrophage-induced stabilization of Snail contributes to Wnt signaling in colon cancer cells and creates a positive feedback loop initiated, and propagated, by macrophage-derived IL-1β." (PMID 20661477, 2010). "Indirectly, 25-OHC has been shown to induce immune cells such as macrophages to express and secrete interleukin-1β (IL-1β), which induces Cox-2 expression in ECs as well as in colon cancer cells." (PMID 21070649, 2010). "We recently demonstrated that macrophages and IL-1β induce Wnt signaling in colon cancer cells through activation of NF-κB-dependent AKT signaling, pathways that have been shown to protect tumor cells from apoptosis." (PMID 20661477, 2010). "In summary, these data established that the levels of IL-1β are elevated in a subset of human colon tumors, and that IL-1β modulates the response of tumor cells to a variety of therapeutic agents both in vitro and in vivo." (PMID 20661477, 2010). "We showed that vitamin D3 inhibited the ability of tumor cells to induce the release of IL-1β from macrophages, and thereby inhibited the subsequent increase in Wnt signaling and growth of colon cancer cells." (PMID 20661477, 2010). "We recently reported that colon tumor cells stimulate macrophages to release IL-1β, which in turn inactivates GSK3β and enhances Wnt signaling in colon cancer cells, generating a self-amplifying loop that promotes the growth of tumor cells." (PMID 20661477, 2010). "IL-1β, IL-6, and IL-10 responses have been exhaustively investigated, particularly in their connection with tumor growth and metastatic spread in colon cancer resection." (PMID 19309495, 2009). "JAK2 has been shown to be activated in response to a wide variety of stimuli and AG-490 to block induced NOS2 expression in IL-1β/TNFα/IFNγ-stimulated human epithelial-like colon carcinoma DLD-1 cells and in IFNγ/LPS stimulated RAW cells." (PMID 18036230, 2007). "VEGF, IL-1β, and IL-1ra concentrations were quantified in tumor samples from patients with colon cancer, and a correlation was observed between the VEGF protein and the IL-1ra: IL-1β ratio within the tumor." (PMID 17096856, 2006). "We investigated interleukin-1β (IL-1β) induction of VEGF expression in colon cancer cells and the mechanism by which this occurs." (PMID 10408390, 1999). "SW620 human colon cancer cells also reached a peak induction of VEGF mRNA 24 h after treatment with IL-1β." (PMID 10408390, 1999). "Similarly, IL-1β enhances colon cancer cell proliferation by inhibiting GSK3β, thereby activating the Wnt pathway and culminating in tumorigenesis." (PMID 40019680, 2025). "Prolonged exposure to IL-1β may enhance the invasiveness of colon cancer cells and facilitate treatment resistance." (PMID 40422233, 2025). "IL-1β has been shown to play a protective role in chemically induced colon cancer mouse models." (PMID 40244135, 2025). "Moreover, IL-1β-induced spheres displayed enhanced stemness and drug resistance in colon cancer cells, accompanied by epithelial-mesenchymal transition." (PMID 40491919, 2025).
colon carcinoma (continued). "Gastrin‐SiO2 microspheres (20 mg kg−1 day−1, 80 μL/10 g), administered by gavage (10–20 s), did not affect the mRNA expression of inflammatory factors (TNFα, MCP‐1, MCP‐2, IL‐1β, and IL‐6) in the intestine and colon cancer promoting markers in the serum (CEA, CA199, and PSA)." (PMID 39950948, 2025). "Additionally, colon cancer cells can stimulate IL-1β production from THP1 macrophages, activating the Wnt signaling pathway and promoting cancer cell growth." (PMID 39744582, 2025). "Similarly, it has been shown that Zinc finger protein 70 increases the IL-1β secretion in macrophages, promoting colon cancer cell proliferation (HCT-116)." (PMID 39769450, 2024). "A study showed that Bifidobacterium longum isolated from breast milk can relieve colon cancer by significantly increasing the concentration of IL-1β, an anti-inflammatory factor, and decreasing the concentration of IL-6, a pro-inflammatory factor in colon cancer model mice." (PMID 38540948, 2024). "The current results demonstrated elevated levels for TNF-α (376.2 ± 20.9 vs. 94.8 ± 18.3) and NFκB (3,287.7 ± 264.7 vs. 724.5 ± 79.1) and for the downstream products IL-1β (446.9 ± 23.3 vs. 85.25 ± 13.5) and IL-6 (258.0 ± 34.7 vs. 20.7 ± 9.8) in the colon cancer group versus the saline group." (PMID 38645563, 2024). "Furthermore, a mouse model of adenomatous polyposis coli (APC) colon cancer showed significant levels of IL-1B and IL-1A." (PMID 37894904, 2023). "Moreover, IL-1β enhanced colon cancer cells’ ability to self-renew, which is a crucial characteristic of CSCs." (PMID 37834263, 2023). "ZEB1 mediated IL‐1β expression and promoted colon cancer cell stemness and invasiveness." (PMID 37192201, 2023). "Moreover, it was shown that sialyl Lewis X-expressing antigens on colon cancer cells act as ligands for selectins, induced by IL-1β, on human liver endothelial cells." (PMID 37409130, 2023). "Furthermore, an in vitro study also demonstrated that the addition of TNF-α, IL-1β, and IL-6 factors to the conditioned medium of activated macrophages significantly triggered the proliferation and immigration of human colon carcinoma cells." (PMID 36559282, 2022). "Streptococcus infection could activate the NLRP3 inflammasome and induce IL-1β secretion, which was previously shown to promote colon cancer." (PMID 35865926, 2022). "In one way, eATP mediates chemotactic effects on myeloid cells in thymoma and colon cancer and promotes the secretion of inflammasome-dependent interleukin 1 beta (IL-1β) and IL-18, which are critical for mature dendritic cells (DCs) to prime cytotoxic T lymphocytes." (PMID 35769718, 2022). "What is more, ZFP91 can not only activate HIF-1α through NF-κB/p65 but also positively regulate the production of inflammatory cytokine IL-1β in macrophages by activating the MAPKs and atypical caspase-8 inflammasome, which advances the proliferation and tumorigenesis of colon cancer." (PMID 36358661, 2022). "Specifically, these shared pathways with IBD were linked to inflammation (TNF, IL-1A, IL-1B, NFkB, IL-6) and growth (TREM1, TGFB1), while other pathways shared with colon cancer were associated with colorectal metastatic signaling, growth (TREM1, NFkB and HMGB1) and inflammation (IL-8, IL-6)." (PMID 35323693, 2022). "We tested the effect of IL-1β on 5-FU treatment in the AA and CA colon cancer cell lines." (PMID 36531053, 2022). "In the present study, we assessed for the first time, the response to the pro-inflammatory cytokine IL-1β in AA colon cancer in vitro models, with the purpose of better understanding the mechanisms behind the lower response to treatment as well as overall poor prognosis in AA patients." (PMID 36531053, 2022). "Likewise, we detected the colon cancer prognostic biomarker CXCL8 and its associated pro-inflammatory cytokines (IL1-β, TNF-α, IFN-γ and IL-6) in the serum of mice in each group." (PMID 35922850, 2022).
colon carcinoma (continued). "Our results suggest a differential expression of inflammatory genes and proteins that might regulate the different response to IL-1β between AA and CA colon cancer cell lines." (PMID 36531053, 2022). "We believe our study represents the first in vitro utilization of AA colon cancer cell lines to investigate a role for IL-1β in tumor promotion and response to 5-FU.To our knowledge, our cells lines represent the only in vitro colon cancer model derived from AA patients." (PMID 36531053, 2022). "We subsequently tested if the altered expression in IL-6 and IL-1β would affect the tumor microenvironment and modify signaling in colon cancer cells by treating COLO205 cells with the supernatant from THP1 transfected cells combined with regular growth media (1:1) followed by cell growth for 72 h." (PMID 35499706, 2022). "Secretion of IL-1β from macrophages, via the stimulation of colon tumor cells, inactivates glycogen synthase kinase 3β and enhances Wnt signaling, which in turn promotes colon cancer cell growth by producing a self-amplifying loop." (PMID 35954156, 2022). "Furthermore, in vitro studies have shown that colon cancer cells stimulate macrophages to release IL-1β, which in turn enhances Wnt signaling in colon cancer cells, generating a self-amplifying loop promoting tumor growth." (PMID 34108518, 2021). "IL1B also plays a role in promoting the stemness and invasiveness of colon cancer cells." (PMID 35008304, 2021). "Contrasting effects of IL-1β have been described on colon cancer incidence." (PMID 32635472, 2020). "IL-1β reduced genome methylation of human colon cancer epithelial Caco2 cells and induced CpG demethylation at specific sites in the promoters of the inflammatory cytokine genes IL-6 and IL-8, but not of the IL10 gene promoter, resulting in their increased expression levels." (PMID 31557902, 2019). "The aim of this study was to investigate whether S.t-ΔpGlux/pT-ClyA inhibits colon cancer growth and recurrence by promoting increased IL-1β production." (PMID 31754923, 2019). "IL-1β has also been shown to affect DNA methylation in differentiated colon cancer cells." (PMID 31557902, 2019). "Macrophages producing IL1β could stimulate growth of colon cancer cells by activating GSK3β/Wnt signaling." (PMID 31333662, 2019). "For example, in one study, MCP-1 was shown to regulate IL-1β in a feedback loop and since we showed that in colon cancer MK2 regulates the majority of IL-1β production in the colon tumor microenvironment, it is important to further study the downstream inflammatory effects of the MK2 pathway." (PMID 30298062, 2018). "Moreover, 10-hydroxy-2-decenoic acid, the major lipid constituent in RJ, was found to exert anti-inflammatory effects in human colon cancer cells via inhibiting NF-κB, which further suppressed the release of IL-1β and TNF-α." (PMID 30544760, 2018). "In conclusion, our study shows that MK2 activity in colon tumors and colon tumor-associated macrophages is a critical regulator of not only IL-1β, IL-6, and TNF-α but also MMM, which has not previously been reported." (PMID 30298062, 2018). "IL-1β may promote epithelial mesenchymal transitions and stem cell development, as well as contribute to the malignancy, of colon cancer." (PMID 28865486, 2017). "In colon cancer, IL-1β promoted epithelial mesenchymal transitions and stem cell development." (PMID 28865486, 2017). "It is suggested that GEN-27 could prevent IL-1β-induced cancer cell growth and could potentially be used as a chemopreventive agent against inflammation-related colon cancer." (PMID 27057094, 2016). "Peritoneal fluids collected at surgery initiation and after surgery were evaluated for their effect on migration potential of human colon cancer cells using an in vitro scratch assay and on TNF-α, IL-1β, IL-6, and IL-10 levels using bead-based fluorokine-linked multianalyte profiling." (PMID 26819599, 2016).
colon carcinoma (continued). "The adhesion of CC531, Caco2 and HT29 colon carcinoma cell lines to an autologous monolayer of rat mesothelial cells pre-incubated with factors released after surgical trauma (IL-1β and EGF) resulted in at least 60% more cell adhesion in a dose-dependent manner." (PMID 22296757, 2012). "The importance of Zeb1 in IL-1β-induced EMT in colon cancer cells is further highlighted in Zeb1 knockdown HCT-116 cells, which display a close association between the lack of EMT and the disappearance of IL-1β-induced repression of E-cadherin transcription in these cells." (PMID 23174018, 2012). "Although, it is known that IL1B polymorphisms are associated with tumor recurrence in stage II colon cancers, the function of this gene has not been clarified in CRC." (PMID 23155391, 2012). "Using a colon cancer cell line and primary colon cancer cells, we have demonstrated that IL-1β may act via Zeb1 to promote EMT and stem cell development in colon cancer cells, which may contribute to colon tumor malignancy." (PMID 23174018, 2012). "Thus, IL-1β and Zeb1 can be potential therapeutic targets aimed at cancer stem cells in the development of novel treatments for colon cancer." (PMID 23174018, 2012). "Our findings indicate that IL-1β may promote colon tumor growth and invasion through activation of CSC self-renewal and EMT, and Zeb1 plays a critical role in these two processes." (PMID 23174018, 2012). "Here we investigated the role of IL-1β in colon cancer stem cell (CSC) development." (PMID 23174018, 2012). "Importantly, IL-1β induces cellular morphological changes in colon cancer cells that are consistent with the acquisition of EMT phenotype as characterized by the loss of E-cadherin expression." (PMID 23174018, 2012). "Moreover, 25-OHC in combination with IL-1β has been shown to stimulate human colon carcinoma cells (Caco-2) to produce IL-8, which in turn is a promoter of angiogenesis by stimulating endothelial cells proliferation, survival, migration, and MMP-2 production." (PMID 21070649, 2010). "Like THP1 macrophages, normal peripheral blood monocytes restored the MMP and prevented activation of caspase 8 and cleavage of PARP in TRAIL-treated tumor cells (data not shown), which is consistent with the ability of colon cancer cells to induce IL-1β release from peripheral blood monocytes." (PMID 20661477, 2010). "In this study we demonstrated that TRAIL induced apoptosis of colon cancer cells is inhibited by macrophage derived IL-1β, and showed that macrophages and recombinant IL-1β counteract TRAIL-induced apoptosis through activation of Wnt signaling and stabilization of Snail in tumor cells." (PMID 20661477, 2010). "We have observed that human colon cancer cells (HT-29) are able to secrete granulocyte-macrophage-colony stimulating factor, granulocyte-colony stimulating factor and macrophage-colony stimulating factor when stimulated with cytokines (IL-1β and TNF-α)." (PMID 11953891, 2002). "Indeed, PPARγ agonists have been shown to suppress monocyte elaboration of inflammatory cytokines and to inhibit IL-1β-induced expression of IL-8 in colon cancer cell lines." (PMID 12454768, 2002). "In the present study we confirm our previous observations that human colon cancer epithelial cells have the ability to produce GM-CSF, G-CSF and M-CSF in response to cytokines commonly found in the inflammatory responses (IL-1β and TNF-α), including those that accompany tumour formation." (PMID 11953891, 2002). "HT29 human colon cancer cells were treated with IL-1β for various periods." (PMID 10408390, 1999). "Additionally, IL-1β activates miR-146a, which in turn targets p38, ERK, and JNK MAP kinases, along with downstream transcription factors GATA2, c-Fos, and c-Jun, that are implicated in metastatic progression in colon cancer cells." (PMID 38671854, 2024).